TNF (tumor necrosis factor)
Diseases named in the same sentence as TNF in open-access papers (continued):
Sharing a sentence is not in itself a finding about the gene and the disease.
Hypertension (continued). "Monocyte recruitment is the key factor in the development of vascular inflammation, followed by adhesion molecules (VCAM-1 and ICAM-1), inflammatory factors (TNF-α and IL-6), and chemokines (CCL2, CXCL5, CXCL8, and CXCL10) released during hypertension." (PMID 34335249, 2021). "In hypertension induced by angiotensin II (AngII) administration with high salt (HS) intake, intrarenal angiotensinogen (AGT) and tumor necrosis factor‐alpha (TNF‐α) levels increase." (PMID 34427402, 2021). "Basal levels of proinflammatory cytokines are increased in patients with hypertension, where ILs-6, -8, -18, transforming growth factor (TGF)-β, and tumor necrosis factor (TNF)-α are in disequilibrium with anti-inflammatory cytokines (ILs-4 and -10)." (PMID 34441038, 2021). "The findings of reduced PGRN/TNF ratio as an independent predictor of SBP, ascertain the key role of imbalance in pro- and anti-inflammatory environment in hypertension." (PMID 32424472, 2020). "In this review, we focused on the central and peripheral effects of ADAM17-mediated shedding of inflammatory cytokines such as IL-6, TNF-α, and FKN, and their possible role in hypertension." (PMID 32848763, 2020). "Findings of reduced PGRN/TNF ratio, and it being an independent predictor of SBP, ascertain the key role of imbalance in pro- and anti-inflammatory environment in hypertension." (PMID 32424472, 2020). "Individuals with T2DM in combination with arterial hypertension exhibit maximum TIMP-1 levels and TIMP-1:MMP-2 and TIMP-1:MMP-9 ratios, as well as enhanced secretion of tumor necrosis factor alpha (TNF-α), interleukin-16 (IL-6), and IL-17." (PMID 33419373, 2020). "TNF-α concentration is significantly higher in the group of patients with T1DM and high blood pressure." (PMID 33202729, 2020). "Pro-inflammatory cytokines TNF-a and IL6 maintain hypertension by inducing endothelial proliferation and increasing vascular permeability and blood volume." (PMID 31327319, 2019). "The current study indicates that feeding a high-fat diet induces much more inflammatory cytokine TNFα production in the PVN, which activates NADPH oxidase activity to increase ROS generation for enhancing AAR, SNA and hypertension in rats with OH." (PMID 31391086, 2019). "As expected, the levels of the inflammatory cytokines IL-6 and TNF-α were elevated in the aortas of HFpEF pigs and significantly decreased with dapagliflozin treatment, suggesting that dapagliflozin could attenuate the hypertension-induced macrovascular inflammatory response." (PMID 31429767, 2019). "Etanercept, a clinically available recombinant TNF-α receptor that reduces the biological activity of TNF-α, reduces mean arterial pressure in a female mouse model of SLE, suggesting that TNF-α mechanistically contributes to the development of hypertension." (PMID 31694260, 2019). "Previous studies suggest that pro-inflammatory cytokines (PICs) such as TNF-α and IL-1β were increased within the PVN of spontaneous hypertensive rats, and lead to the development of hypertension symptoms." (PMID 31708733, 2019). "Although the study subjects were overweight-to-obese and had hypertension or MetS, they were metabolically healthy (excluding T2DM), limiting a further reduction of parameters such as glucose, hs-CRP, and hs-TNFα which were already low at baseline." (PMID 31068933, 2019). "Interleukin (IL)-1B, IL-6, IL-18, tumor necrosis factor (TNF)-α and interferon (IFN)-γ are increased in LVH and hypertension, with all these pro-inflammatory cytokines activating IDO." (PMID 31434333, 2019). "Measurements of serum concentrations of TNF-α, MDA, FRAP in hypertension patients was done in both the groups." (PMID 31666827, 2019). "To test the effect of 8 weeks of aerobic ExT or PVN infusion of TLR4 inhibitor in hypertension, we respectively examined the PVN levels of TNF-α and IL-1β mRNA and protein by RT-qPCR, western blotting, and immunofluorescence staining." (PMID 31708733, 2019).
Hypertension (continued). "This suggests that the increased TNFα level in the PVN of rats with OH can promote the enhancement of AAR involving sympathoexcitation and hypertension." (PMID 31391086, 2019). "Chronic systematic suppression of TNFα with PTX during the HFD period blunted TNFα production and attenuated the enhanced the AAR, SNA and hypertension in rats with OH." (PMID 31391086, 2019). "Therefore, according to our results, the interaction between central obesity and hypertension may lead to a reduction in anti-inflammatory adipokines, adiponectin, and further increases in pro-inflammatory adipokines and TNF-α compared with female subjects with central obesity or hypertension alone." (PMID 29636702, 2018). "For example, a high level of tumor necrosis factor (TNF-α), a pro-inflammatory cytokine, developed in response to oxidative stress in l-NAME-induced hypertension has been reported." (PMID 30347737, 2018). "Intermediate monocytes are not only a biomarker of inflammation in hypertension, but their acquisition of CD16 arms them to possess cytotoxic function and to produce TNFα." (PMID 29800237, 2018). "Inflammatory cytokines such as interleukin and tumor necrosis factor-α (TNF-α) can inhibit vasodilator release and result in aggravation of hypertension by downregulating endothelial nitric oxide synthase (eNOS) and damaging endothelium cells." (PMID 30345307, 2018). "Correspondingly, in current study, the increased low-grade inflammation in inner of aortae (elevated pro-inflammatory cytokines TNFα, MCP-1, and ICAM-1) underpinned at least some of the pathological basis of the hypertension of the KKAy mice." (PMID 29731737, 2018). "Azra Mahmud also founded that arterial stiffness is related to systemic inflammation including TNF-α, IL-6 and hs-CRP in essential hypertension." (PMID 29433526, 2018). "T cells that expand in pathology and promote development of insulin resistance, atherosclerosis, and hypertension include predominantly IFN-γ-producing Th1 (CD4+) and Tc1 (CD8+) cells, producing IFNγ and TNF, and IL-17 producing Th17 cells." (PMID 28838042, 2017). "Essential hypertension (EH) patients exhibited a marked increase in CMV IgG antibody, CRP, TNF-α, and IL-6 levels." (PMID 28837559, 2017). "The aim of the current study was to examine the effects of treatment of hypertension and CAD on serum levels of IL-6, IL-8, TGF-β and TNF-α." (PMID 28033321, 2016). "Correlations among age, weight, BMI, IL-6, IL-8, TNF-α and TGF-β within group 2 (patients with hypertension and CAD)." (PMID 28033321, 2016). "TLR4 signaling is a major source of pro-inflammatory cytokines, such as TNF-α, and blockade of TLR4 in the brain has been shown to prevent cardiac dysfunction in experimental models of heart failure and hypertension." (PMID 25811788, 2015). "When compared with subjects without the H. pylori antibody, subjects with the H. pylori antibody had higher rates of hypertension, HOMR-IR (including index >2, >2.5 or >3), and higher diastolic/ systolic blood pressure, cholesterol and TNF-α." (PMID 26020514, 2015).
Hypertension (continued). "Importantly, though antagonism of TNF-α by administration of a soluble receptor tended to decrease the hypertension associated with placental ischemia, this was not significant, suggesting that its hypertensive effects are only a part of a much broader response." (PMID 26347650, 2015). "Another major finding in the current study was the identification of the central role of TNF-α in the effect of p38 MAPK and JNK signaling on Ang II-induced hypertension and cardiac hypertrophy." (PMID 26378790, 2015). "In the current study, the average values of CRP, IL-6 and TNF-α in patients with chronic TAAD and hypertension tended to be higher than those in the healthy controls (Chronic TAAD vs. Healthy, P = 0.06; uHT vs. Healthy, P = 0.09)." (PMID 25592634, 2015). "Taken together, these data suggest that Ang II-induced cardiac hypertrophy and hypertension are dependent on the presence of NADPH oxidase, increased oxidative stress, and activation of NF-κB, and require concomitant generation of TNF-α." (PMID 26378790, 2015). "Several studies in vitro and in vivo studies suggest the existence of cross-talk between TNFα and the renin-angiotensin system (RAS), which is an important part of the pathogenesis of hypertension." (PMID 24665369, 2014). "Our present observations complement those prior findings and show that blockade of TNF by ICV administration of etanercept into the brain protects rats against Ang II-dependent cardiac hypertrophy and hypertension." (PMID 23691105, 2013). "The common area between the hypertension only- and hypercholesterolemia plus sham groups showed up-regulated focus genes related to UBC, APP, SERPINB2, TNF and HNF4A, and down-regulated focus genes related to UBC." (PMID 23874591, 2013). "Hypertension induced by IP infusion of LPS was accompanied by an increase in plasma levels of CRP, TNFα, and IL-1β, detected on day 7 or 14 after infusion of the endotoxin." (PMID 22958438, 2012). "More importantly, proinflammatory cytokines (PIC), such as tumor necrosis factor alpha (TNF), interleukin (IL)-1β and IL-6, play important roles in hypertension and heart diseases." (PMID 23056347, 2012). "Although studies in experimental animal models indicate that both TNF and ANGII are involved in the pathophysiology of hypertension, possible interactions between these factors have not been explored at the mitochondrial level." (PMID 23056347, 2012). "Production of pro-inflammatory cytokines such as tumor necrosis factor-α (TNF-α) can be stimulated by various pathophysiological phenomena including modified low density lipoprotein (LDL), hemodynamic stress and hypertension." (PMID 19736220, 2011). "A study in 12-week-old male rats with spontaneous hypertension (SHR) showed that polyphenols present in lychee seeds can inhibit the TNF signalling pathway, in which TNF-α is a key mediator of inflammation, whose excessive activation contributes to increased blood pressure." (PMID 41226708, 2025). "Combined with protein interaction network analysis, the potential primary targets of berberine in treating hypertension may include AKT1, BCL2, EGFR, STAT3, and TNF." (PMID 41567631, 2025). "But TNFα and IL-1ß are neither correlated with patients with hypertension (r2 = 0.30, p = 0.005) nor with patients without hypertension (r2 = 0.35, p < 0.0068)." (PMID 38216681, 2024). "Chronic pericyte exposure to TNFα, IFN-γ, or IL-1β (e.g., during the longer course of hypertension) compromises pericyte function, leading to BBB disruption, which is mediated through the decrease of angiopoietin 1 or platelet-derived growth factor receptor β (PDGFRβ) and its signaling." (PMID 39495252, 2024). "Our analyses showed that TNF, HSP90AA1, NFKB1, PPARG, SIRT1, PTGS2, and RELA might be α-MG’s potential therapeutic targets for hypertension, laying groundwork for further investigation into its pharmacological mechanisms and clinical uses." (PMID 39592923, 2024).
Hypertension (continued). "Mice lacking TNFα, specifically in the renal parenchyma, were protected from angiotensin II-induced hypertension and organ damage but increased endothelial nitric oxide synthase expression in kidneys." (PMID 38256155, 2024). "Twenty-week-old male SHRs showed high blood pressure (BP), cardiac remodeling, cardiac dysfunction, higher levels of markers of oxidative stress [malondialdehyde (MDA)] and inflammation [tumor necrosis factor-α (TNF-α)], as well as lower levels of a marker of vascular function (nitric oxide)." (PMID 39599656, 2024). "Also, a recent article has disclosed higher levels of IL-6, TNF-α, and hs-CRP in uncomplicated hypertension." (PMID 37759223, 2023). "Moreover, abundant ROS and inflammatory factors, including IL-6 and tumor necrosis factor-α (TNF-α), contribute to comorbid hypertension and anxiety in rats." (PMID 37273529, 2023). "In this case, the PGRN/TNF-α ratio has been shown to be one of the independent predictors of high systolic blood pressure (SBP), implying the importance of the inflammatory components involved in hypertension." (PMID 36658641, 2023). "Moreover, IL-6 and TNF-α also promote the production of RAAS components, especially angiotensinogen, further contributing to systemic and local angiotensin II formation and hypertension development." (PMID 37180779, 2023). "The levels of the pro-inflammatory cytokine TNF-α were increased in hypertensive subjects, 516.1 pg/mL (279.7–856.3 pg/mL), p < 0.01 compared to subjects without hypertension, 197.7 pg/mL (142.0–197.7 pg/mL)." (PMID 36671026, 2023). "Furthermore, T-cells are shown to be deregulated in hypertension and CVDs, resulting in an increased production of the pro-inflammatory cytokines IL-6, IL-7, IFN-γ, and TNF-α." (PMID 37238657, 2023). "Among them are the Toll-like receptor signaling pathway, PI3K-Akt signaling pathway, MAPK signaling pathway, TNF signaling pathway, NOD-like receptor signaling pathway, NF-κB pathway, and renin-angiotensin pathway which are strongly correlated with hypertension." (PMID 36046450, 2022). "While not intensively studied in animal models of hypertension, clinical studies have consistently found men to have higher circulating TNF-α levels compared to women." (PMID 35413930, 2022). "For T2D patients with hypertension the TNF-α (β = − 0.297, p = 0.000) and for T2D patients without hypertension OPG had significant contribution to decreased BRS (β = − 0.344, p = 0.004) in the test group." (PMID 36085061, 2022). "Predictive of MAC were TNF-α, HOMA C-peptide, and especially hepatic steatosis and hypertension." (PMID 36143268, 2022). "TNF-α and OPG levels were higher in T2D patients with hypertension." (PMID 36085061, 2022). "To elucidate the mechanisms by which hypertension induces bone resorption, we examined the mRNA expression levels of proinflammatory cytokines and factors and found that SSHTN mice had elevated TNF-α mRNA, protein expression, and serum level in comparison to normal controls." (PMID 35445013, 2022). "Interestingly, hypertension and cardiac hypertrophy were alleviated by ICV administration of Etanercept (TNF-α inhibitor)." (PMID 33967677, 2021). "ssociations were essentially not modified by further adjustment for current depressive episode, antidepressant use, history of CVD, hypertension, B vitamins (PLP, riboflavin) and low-grade inflammation (composite score of CRP, SAA, sICAM-1, IL-6, IL-8 and TNF-α)." (PMID 34409496, 2021). "VNS has not yet been tested in human hypertension, but has been used in epilepsy and in RA, demonstrating lowering of circulating TNF-α, IL-1-β, and IL-6 levels and improvement in disease activity." (PMID 34698811, 2021).
Hypertension (continued). "Furthermore, the DCs activated by isolevuglandin adducts stimulate the T cells to release IL-17, TNF-α, and IFN-γ, leading to hypertension and hypertension-damaged organ tissue (kidney, heart, vascular system)." (PMID 34884617, 2021). "Moreover, TNF-α downregulates PKG1 through miR-155-p, inducing SMC phenotype and function alteration, which is important in inducing hypertension in inflammation." (PMID 33807627, 2021). "However, it has already been reported that whey protein supplementation reduces pro-inflammatory cytokine IL-6 and tumor necrosis factor alpha (TNF-α) levels in patients with ischemic stroke, chronic obstructive pulmonary disease, and hypertension." (PMID 34858171, 2021). "However, the interactive roles for TNF‐α and intrarenal AGT formation in the pathophysiology of hypertension induced by HS intake, particularly in its non‐dipping blood pressure pattern, are not yet clearly understood." (PMID 34427402, 2021). "TNF-α was not significantly correlated with age, BMI, hypertension, smoking, AHI, blood glucose, or HbA1c." (PMID 34676249, 2021). "Increase in ADAM17 levels in the paraventricular nucleus (PVN) and subfornical organ (SFO) have been reported to elevate the expression of inflammatory (TNF-α, IL-β, and COX-2) and excitatory mediators, which drive the sympathetic excitation-mediated hypertension and heart failure." (PMID 32848763, 2020). "Furthermore, TNF-α knockout mice demonstrated a rise in endothelial NOS production and prevented the hypertension development in a model of Ang-II infusion compared to wild type controls." (PMID 32848763, 2020). "Neither IFNγ (β = 0.01, p = 0.71) nor TNFα (β = 0.07, p = 0.06) reached statistical significance in their individual associations with NCB (fully adjusted model included age, sex, hypertension, hyperlipidaemia, waist: hip ratio and statin use)." (PMID 32646751, 2020). "Central inhibition of AT1-R, TNF-α synthesis or microglial activation significantly attenuated either HFD- or leptin-induced upregulation of RAS activity, inflammation in the LT and PVN, and HFD or leptin sensitization of ANG II-induced hypertension." (PMID 32760236, 2020). "Since in IUGR (without coexisting hypertension) no sign of inflammation was noted, i.e., the levels of TNF-α, IL-6, and IL-8 were comparable to normal controls, chronic oxidative stress in the pathology is not very probable." (PMID 32685085, 2020). "In general, among the patients with hypertension combined with CHF with preserved LVEF, the level of proinflammatory status indicators (CRP, TNF-α, IL-6) corresponded to the normative range of values; however, it was significantly higher in males than in females." (PMID 35366254, 2020). "Peripheral administration of TNF-α and IL-1β was also reported to reach the SFO, which lacks a blood brain barrier and dramatically increased mean blood pressure, heart rate and renal sympathetic nerve activity, resulting in hypertension." (PMID 32848763, 2020). "Other well defined adaptive immunity cytokines in hypertension include IFN-γ and TNF-α." (PMID 31321561, 2019). "To investigate whether TNFα in the PVN is involved in sympathetic activation and hypertension in OH, we firstly examined the mRNA and protein expressions of TNFα." (PMID 31391086, 2019). "Elevated proinflammatory cytokines (PICs) are transported into the PVN primarily via the circumventricular organs, and the accumulated PICs such as tumor necrosis factor α (TNFα) in the PVN can regulate SNA and cardiovascular function in rats with hypertension or chronic heart failure (CHF)." (PMID 31391086, 2019). "Tumor necrosis factor-α, inhibitor improves clinical symptoms however their outcome on high blood pressure has not been investigated." (PMID 31666827, 2019).